EGFR (epidermal growth factor receptor)
Diseases named in the same sentence as EGFR in open-access papers (continued):
Sharing a sentence is not in itself a finding about the gene and the disease.
squamous cell carcinoma (continued). "Therefore, both immunohistochemical assay and PCR-based techniques showed close agreement in the use of p16INK4A and EGFR but not p-EGFR as clinically useful surrogate biomarkers for high risk HPV infection in HIV/AIDS-associated squamous cell carcinoma of conjunctiva." (PMID 24572046, 2014). "In analyses of EGFR autophosphorylation and cell proliferation ([3H]-thymidine incorporation) in human epidermoid carcinoma A431 cells, two chloro-derivatives exhibited stronger inhibitory effects than GM3 on EGFR activity." (PMID 24944646, 2014). "We describe three confirmed cases of squamous cell carcinoma (SCC) of the lung with metastasis to the gastrointestinal (GI) tract, with two having epidermal growth factor receptor (EGFR) exon 19 deletions in all available specimens." (PMID 24171005, 2013). "For some patients the choice seems relatively clear (for example, erlotinib in those with EGFR mutant NSCLC whose best response to first-line chemotherapy was stable disease and in those with squamous cell carcinoma)." (PMID 29147317, 2012). "ACR downregulates epidermal growth factor receptor (EGFR) signals due to suppression of transforming growth factor (TGF) α in both HCC cells and human squamous cell carcinoma cells undergoing apoptosis." (PMID 21214951, 2011). "In the literature, few data regarding EGFR and K-RAS status in squamous cell carcinoma of the anal canal is available." (PMID 20459770, 2010). "The EGFR inhibitors have already demonstrated activity in several advanced stage cancers including NSCLC, colorectal, and squamous cell carcinomas of the SCCHN." (PMID 15238978, 2004). "A synergistic inhibition of EGF receptor autophosphorylation by alpha EGFR ior egf/r3 and GM3 was also observed in the human epidermoid carcinoma cell line A431." (PMID 9010029, 1997). "EGFR and KRAS G12C mutations were found almost exclusively in adenocarcinoma (7.8% and 13.3%, respectively), with very low prevalence in squamous carcinomas or NOS/other categories/not classified (p < 0.001 for both)." (PMID 40867330, 2025). "Adjuvant immunotherapy improved DFS in patients with completely resected NSCLC, particularly those who were EGFR-negative, had PD-L1 levels of 1–49%, had non-squamous cell carcinoma, or never smoked." (PMID 40265009, 2025). "Overall, our findings suggest that adjuvant immunotherapy improves DFS in patients with resected NSCLC, particularly in those who are EGFR-negative, have PD-L1 expression of 1–49%, have non-squamous cell carcinoma, and have never smoked." (PMID 40265009, 2025). "EGFR alterations occurred in 19% of non-squamous carcinomas and 6% of squamous cell carcinomas (SCCs), suggesting an intermediate East–West pattern." (PMID 41465119, 2025). "The NCCN NSCLC Panel advocates for the testing of EGFR mutations and other biomarkers in patients diagnosed with metastatic non-squamous NSCLC or NSCLC NOS, as well as in cases of squamous cell carcinoma." (PMID 41153394, 2025). "EGFR amplification was observed in 6 of 66 OED cases (9.1%), including 2 patients with mild dysplasia and 3 patients with moderate dysplasia; the remaining patient later developed metachronous squamous cell carcinoma and died of tumor progression." (PMID 41463200, 2025). "Overall, EGFR/ALK profiling was significantly more often unfeasible in squamous cell carcinoma (17.5%, or 28 of 160 patients) than in non-squamous cell carcinoma (10.4%, or 60 out of 578 patients)." (PMID 39083479, 2024). "Epidermal growth factor receptor (EGFR) tyrosine kinase inhibitors (e.g., erlotinib, gefitinib, and afatinib), employed as first-line treatments for advanced NSCLC, demonstrate pronounced efficacy primarily against histotypes other than squamous carcinoma." (PMID 37686123, 2023). "Similarly, in squamous cell carcinoma, PGE2 promotes tumor cell growth and invasion by the activation of the EP2 receptor, which in turn promotes EGFR transactivation via protein kinase A (PKA) and cSrc activation." (PMID 37190301, 2023).
squamous cell carcinoma (continued). "PAI using a fluorescent anti-epidermal growth factor receptor (EGFR) affibody molecule (ABY-029, eIND 122,681) with untargeted IRDye 700DX carboxylate was compared to ABY-029 alone in an oral squamous cell carcinoma xenograft mouse model at 3 h after dye administration (n = 30)." (PMID 34651290, 2023). "When the folate moiety was replaced with anti-EGFR nanobody, the anticancer activity of ClyA nanobody increased compared to low-cysteine ClyA (the IC50 values of 7.2 and 17.1 nM, respectively, against A431 epidermoid carcinoma cells overexpressing EGFR)." (PMID 36158673, 2022). "Other studies have shown that LIPI is an independent prognostic factor for chemotherapy in wild-type EGFR patients and for EGFR-TKI therapy in EGFR-mutated subsets, but not for squamous cell carcinoma." (PMID 36292049, 2022). "EGFR overexpression was significantly correlated (p = 0.000; χ2 = 85.409) with various grades of dysplasia, and well-differentiated (WDSCC) and moderately differentiated squamous cell carcinoma (MDSCC)." (PMID 36010285, 2022). "Only adenocarcinoma or squamous cell carcinoma, and all negative for epidermal growth factor receptor, anaplastic lymphoma kinase, proto-oncogene tyrosine-protein kinase-1 and proto-oncogene B-Raf." (PMID 33854617, 2021). "Among the 16 patients with EGFR mutations, 15 had adenocarcinomas, 1 was not-otherwise-specified NSCLC, and none were squamous cell carcinomas." (PMID 34696229, 2021). "Approximately 20% of patients had an EGFR mutation, half of patients had wild‐type, and approximately 30% of patients, including patients with squamous cell carcinoma, were not identified with EGFR status." (PMID 33017518, 2020). "The effect of IPA-3 (PAK1 inhibitor) plus auranofin (PKCι inhibitor) combination was evaluated by cell viability assay, colony formation and western blotting assay, using three types of NSCLC cell lines: EGFR or KRAS mutant adenocarcinoma and squamous cell carcinoma with PAK1 amplification." (PMID 31660987, 2019). "Regarding the NSCLC patients, 6 of them presented with adenocarcinoma (only one with an EGFR mutation and no one with ALK/ROS mutations) and 4 of them with squamous cell carcinoma." (PMID 29874299, 2018). "Interestingly, inhibition of EGFR signaling was also shown to attenuate POSTN-mediated cell migration and invasion in esopahageal squamous cell carcinoma supporting a relationship between POSTN and EGFR pathway." (PMID 29946533, 2018). "All patients with squamous cell carcinoma were smokers, and the majority of non-smokers were among patients with EGFR and ALK genes abnormalities." (PMID 28969070, 2017). "PD-L1 expression was higher in squamous cell carcinoma, wild-type EGFR, and smokers than in non-squamous carcinoma, mutant EGFR, and never smokers, respectively." (PMID 29152077, 2017). "One phase II clinical trial showed that EGFR-TKI erlotinib had activity in a small number of patients with ESCC, with partial responses in 15% patients (2 of 13) and stable disease in 54% (7 of 13) patients with squamous carcinoma." (PMID 27013591, 2016). "The EGFR mutation rate in squamous cell carcinoma is reported to be approximately 5%, therefore, most squamous cell carcinoma patients do not benefit from EGFR targeted therapy." (PMID 27072585, 2016).
squamous cell carcinoma (continued). "Furthermore, in advanced NSCLC patients treated with EGFR-TKIs, high CEA and/or low Cyfra21-1 levels significantly correlated with higher responses and longer survival, especially in patients with unknown EGFR mutation status or with squamous cell carcinoma diagnosis." (PMID 27072585, 2016). "Although anti-EGFR therapies have been in clinical use for almost a decade in patients with squamous cell carcinoma, there are no biomarkers that successfully predict patient response to treatment." (PMID 26120042, 2015). "This is similar to what is observed with squamous cell carcinomas of the head and neck, although EGFR expression has not universally correlated to better response to EGFR-directed therapies across all cancer types." (PMID 26498363, 2015). "As an example, ERK2 but not ERK1 regulates the crosstalk between Met and EGFR in squamous cell carcinoma cell lines." (PMID 26247939, 2015). "The first demonstration of in vivo effects of afatinib was based on xenografts of the epidermoid carcinoma cell line A431; this model expresses high levels of wild-type EGFR and detectable levels of HER2 and had previously been shown to be sensitive to EGFR-targeted antibody treatment." (PMID 24643470, 2014). "Therefore, we evaluated the correlation between EGFR levels detected by cetuximab and drug sensitivities of CRC cell lines (Caco-2, WiDR, SW480, and HCT116) and the A431 epidermoid carcinoma cell line." (PMID 23824671, 2013). "Previously, we have shown that multifunctional proteoglycan decorin is aberrantly expressed and localized in the nucleus bound to nuclear epidermal growth factor receptor (EGFR) in human dysplastic oral keratinocytes (DOK) and malignant squamous carcinoma cells (SCC-25)." (PMID 22507529, 2012). "No considerable contradiction in EGFR amounts was observed between adenocarcinomas and squamous cell carcinoma in a number of studies." (PMID 23133538, 2012). "CP-358,774 (a potent, selective tyrosine kinase inhibitor of human EGFR, produces cell cycle arrest, and initiates apoptosis in human tumor cells overexpressing EGFR) had an antitumor effect in the EGFR-overexpressing human HN5 and human A431 epidermoid carcinomas." (PMID 22778735, 2012). "The relationship between epidermal growth factor receptor (EGFR) and squamous cell carcinoma in other areas, such as the head and neck, have been well studied resulting in targeted agents against the receptor with improved survival and response to radiotherapy." (PMID 21687574, 2011). "Additionally, the EGFR/RAS/RAF/MEK/ERK pathway and its downstream effectors have primarily been studied in the context of squamous cell carcinomas, which comprise 85–90% of cervical cancers." (PMID 21730982, 2011). "Although amplification was documented in 10% of the squamous carcinomas in this study, we were not able to correlate the presence of EGFR amplification with HPV infection." (PMID 21730982, 2011). "Unlike squamous cell carcinoma of the head and neck or esophagus, EGFR had no influence on prognosis." (PMID 21773035, 2011). "Although EGFR gene amplification was identified in only four cases of tonsil squamous cell carcinoma, it was not possible to correlate this finding with patient outcome." (PMID 20459770, 2010). "This indicates that EGFR and K-RAS mutation analysis is not useful as a screening test for sensitivity to anti-EGFR therapy in anal canal and tonsil squamous cell carcinoma." (PMID 20459770, 2010). "Additionally, ACCS-AS cells showed an increased EGFR expression and other behavioral similarities to NA-SCC, a typical highly proliferative but less invasive squamous cell carcinoma (SCC) cell line of the head and neck." (PMID 18519000, 2008). "The purpose of this study was to evaluate the role of the epidermal growth factor receptor (EGFR) in parathyroid hormone-related protein (PTHrP) expression and humoral hypercalcaemia of malignancy (HHM), using two different human squamous-cell carcinoma (SCC) xenograft models." (PMID 17533397, 2007).
squamous cell carcinoma (continued). "The expression of EGFR was highest in squamous cell carcinomas, but it was not correlated with other characteristics such as age, sex, histological grading, stage or prognosis." (PMID 9662257, 1998). "Expanding upon this with updated data and additional studies, we found that adjuvant ICI therapy significantly prolonged DFS—particularly in EGFR-negative, PD-L1 (1–49%), non-squamous carcinoma, or never-smokers—it did not improve OS in completely resected stage IB–III NSCLC." (PMID 40265009, 2025). "The high proportion of squamous cell carcinomas in patients who were not tested may be partly due to the rare detection of common oncogenic drivers such as EGFR and ALK." (PMID 39494523, 2024). "In those reports, the GGO‐present group tended to have tumors with pathologically low‐grade malignancy, lepidic adenocarcinoma, and EGFR mutation, and the GGO‐absent group sometimes included histological types with poorer prognoses than adenocarcinoma, such as squamous cell carcinoma." (PMID 37105937, 2023). "Interestingly, after further standardization of smoking status, we found that in non-smokers, male patients were more likely to have squamous cell carcinoma and KRAS mutations and less likely to have EGFR L858R mutation than female patients." (PMID 35061839, 2022). "In particular, squamous cell carcinoma (SCC) specific SE regions are cooperatively occupied with TP63 and SOX2 to boost CCAT1 seRNA transcription, CCAT1/TP63/SOX2 complex is bound to SE regions of epidermal growth factor receptor (EGFR) to promote EGFR transcription." (PMID 32278350, 2020). "Similarly, gold nanoparticles bioconjugated with cetuximab to target EGFR were investigated in cell lines overexpressing EGFR and showed consistent and effective targeting both in vitro and in vivo in NMRI nude mice bearing A431 epidermoid carcinoma tumors." (PMID 33291312, 2020). "Moreover, gigantoxin Ι is capable of binding to epidermal growth factor receptor (EGFR) and, therefore, induces morphological changes (rounding of the cells) and tyrosine phosphorylation of the EGFR in cells (was shown using epidermoid carcinoma A431 cell line)." (PMID 30366463, 2018). "In addition, some recently proposed classification schemes are based on the EGFR status according to 2 categories: HPV-positive/P16 positive squamous cell carcinoma and HPV-negative/P16 negative squamous cell carcinoma." (PMID 30150513, 2018). "We first examined the EGF-induced endocytic degradation of EGFR in a panel of NSCLC cell lines, which includes all major histologic subtypes: adenocarcinoma (A549, H1299, HCC827, H1650, and H1975), large cell carcinoma (H460), and squamous cell carcinoma (H226 and SK-MES-1)." (PMID 29976202, 2018). "However, EGFR could also be additionally activated by other mechanisms, such as oxidation in an EGF-dependent manner in squamous carcinoma cells." (PMID 28122935, 2017). "In squamous cell carcinoma resistant to PI3K inhibitors, dimerization of AXL with EGFR activates the PLCγ/PKC/mTOR pathway to sustain tumor progression [61••], and in mesenchymal ovarian tumors and cell lines, AXL dimerized with MET, EGFR, and HER2, leading to sustained ERK activation [62•]." (PMID 28251492, 2017). "To address whether regulation of EGFR’s neddylation is affected under conditions where EGFR expression and activity is expected to be elevated, we created 3D organotypic raft cultures using SCC9 and 1483 squamous cell cancer lines." (PMID 28891468, 2017). "For patients with adenocarcinoma (adenoCA; wild-type [WT] EGFR) and squamous cell carcinoma (squCA), PORT with or without platinum-based CT may be a more suitable adjuvant treatment than EGFR TKI treatment." (PMID 27835914, 2017).
squamous cell carcinoma (continued). "In oral malignant squamous cell carcinoma cells, the nuclear localization of DCN seems to enhance cellular invasion via the nuclear epidermal growth factor receptor (EGFR) pathway, whereas in osteosarcoma cells, DCN-mediated growth arrest is avoided via the protracted activation of membrane EGFR." (PMID 26230845, 2015). "As most previous large-scale studies on EGFR mutations primarily focused on adenocarcinoma, few studies have evaluated the frequency of EGFR mutations in non-adenocarcinoma NSCLC, such as squamous-cell carcinoma, adenosquamous carcinoma, and large-cell carcinoma." (PMID 24351833, 2013). "Moreover, in one of the two positive studies, EGFR was found to have predictive value in oesophageal adenocarcinoma, but not in squamous cell carcinoma." (PMID 17940507, 2007). "Furthermore, using the public database, we found that EGFR was significantly overexpressed in the following subgroups: squamous cell carcinoma, previously received radiation therapy, non-Barretts esophagus, BMI ≤25, alive patients, and non-columnar metaplasia (P < 0.05)." (PMID 36812484, 2023). "Our data suggest that, although EGFR molecular alterations are not as frequent in squamous cell carcinoma as in adenocarcinoma, high expression of this gene occurs in the squamous cell carcinoma and may be the reason for anti-EGFR therapy being efficacious in some squamous cell carcinoma patients." (PMID 29731995, 2018). "In addition to over expression of p16INK4A as potential surrogate marker of HPV-derived squamous cell carcinomas, the development of SCCC in HIV positive patients has been documented to involve activation of epidermal growth factor receptor (EGFR) and its phosphorylated form (p-EGFR)." (PMID 24572046, 2014). "Our subgroup analysis indicated that adjuvant immunotherapy significantly improved DFS in patients with resected EGFR-negative NSCLC and non-squamous cell carcinoma." (PMID 40265009, 2025). "In stage IV, molecular profiling (gene testing for EGFR, ALK, ROS1 and BRAF) was performed in 94.3% of patients with adenocarcinoma, non-specific carcinoma, or nonsmoking squamous cell carcinoma." (PMID 39147937, 2025). "Our results are also consistent with the findings of other studies demonstrating the efficacy of erlotinib in a diverse NSCLC patient population regardless of EGFR status, NSCLC type (adenocarcinoma or squamous-cell carcinoma), TMB, and chemotherapy history." (PMID 38893104, 2024). "Norwegian guidelines have recommended routine EGFR and ALK testing since 2010 and 2013, respectively, for all patients diagnosed with non-squamous cell carcinoma NSCLCs, irrespective of age and stage." (PMID 36900294, 2023). "A similar inhibition of EGF internalization and EGFR phosphorylation has been reported for polychlorinated biphenyls (PCB-126 and PCB-153) and trans-nonachlor in a human epidermoid carcinoma cell line." (PMID 35054855, 2022). "The guidelines recommend searching for EGFR (exons 18–21), ROS1, KRAS, ALK, and PDL1 status in all new diagnosed advanced non-squamous NSCLC and advanced squamous cell carcinomas in never-smokers." (PMID 34898548, 2021). "Originally, the molecular diagnostics of squamous cell carcinoma (SCC) was based on the absence of certain targetable genomic alterations that are commonly found in adenocarcinoma—i.e., EGFR and ALK." (PMID 32604993, 2020). "All patients with adenocarcinoma underwent genetic testing for EGFR/ALK abnormalities, although this was not routinely performed for squamous cell carcinoma." (PMID 32134200, 2020). "In squamous carcinoma cells, TGF‐β induces EGFR activation by producing H2O2 without affecting EGFR protein levels." (PMID 29215776, 2018).